GSTM1 (glutathione S-transferase mu 1)
Diseases named in the same sentence as GSTM1 in open-access papers (continued):
Sharing a sentence is not in itself a finding about the gene and the disease.
Obesity (14 papers, 2006 to 2025). Accumulation of substantial excess body fat. "As a member of phase II drug metabolism-related family catalyst, GSTM1 can detoxify the electrophilic products generated from lipid peroxidation that considers one of the major pathogenic cellular changes in obesity onset and progression." (PMID 33924357, 2021). "Four SNPs were associated with higher obesity risk under heterozygote and dominant models for GSTM1 rs1056806 (C/T), homozygote model for SOD2 rs4880 (A/G), and homozygote and recessive models for GPX1 rs1800668 (A/G)." (PMID 33924357, 2021). "GSTM1 rs1056806 showed a higher risk of obesity under heterozygote comparison (C/T vs. C/C: OR = 2.02, 95%CI = 1.15–3.55, p = 0.015) and dominant models (C/T-T/T vs. C/C: OR = 1.92, 95%CI = 1.11–3.31, p = 0.019)." (PMID 33924357, 2021). "We recently reported that PM2.5 exposure was associated with endothelial cell dysfunction in patients with type 2 diabetes and that factors such as obesity and an elevated HbA1c level, as well as deficient antioxidant gene capability (GSTM1 null), enhanced this deleterious association." (PMID 21169129, 2011). "Similarly, obese GSTM1 null genotypes had, on average, a 22% (95% CI, 12 to 31%) lower TP, whereas with the gene present obesity was associated with only a 3% decline (95% CI, −15% to 10%) compared with nonobese GSTM1 carriers." (PMID 19057702, 2008). "Overall, with regard to the possible systemic influence of GSTM1 on osteoarthritis of the knee or hip joint, it must also be taken into account that noticeable associations with SNPs may be caused by indirect effects, such as an impact on obesity risk factors." (PMID 40630467, 2025). "Inheritance association models revealed that four SNPs to have a prediction value for developing obesity, namely GSTM1 rs1056806 (C/T), SOD2 rs4880 (A/G), SOD3 rs2536512 (A/G), and GPX1 rs1800668 (A/G)." (PMID 33924357, 2021). "Obesity was positively correlated with GSTM1 (r = 0.109, p = 0.035) and SOD2 (r = 0.121, p = 0.046)." (PMID 33924357, 2021). "On the other hand, the similarity between SHS and ambient PM is sufficiently high that the finding of interactions of GSTM1 status and obesity with these exposures in two separate cohorts argues against this being a chance finding." (PMID 19057702, 2008). "Basally ovarian GSTM1 protein was higher in HFHS-induced obese compared with lean females consistent with previous observations in a different obesity model and is of concern because GSTM1 catalyzes the conjugation of GSH to electrophilic compounds such as DMBA metabolites." (PMID 39910959, 2025). "GSTM1 is involved in intracellular transport, cell signaling, and isomerization of steroid hormones and negatively regulates proapoptotic proteins during obesity." (PMID 39910959, 2025). "Several SNPs of the NRF2 gene have repercussions on certain antioxidant enzymes, for example, rs2234694 is related to SOD1, rs2536512 to SOD3, rs1056806 to GSTM1, rs4880 to SOD2 and rs1800668 to GPx1; all were found in obese patients and were associated with increased risk of obesity." (PMID 40428311, 2025). "The association with obesity was greater among individuals with GSTM1- and/or GSTT1-null genotypes than individuals with non-null genotypes." (PMID 31999731, 2020). "In conclusion, our results suggest that GSTM1 and GSTT1 may modify the associations between DTC risk and obesity, alcohol consumption, and possibly hormonal factors." (PMID 31999731, 2020). "The SAPADIA cohort team previously reported on the modifying effect of antioxidative GST gene polymorphisms (GSTM1 and GSTT1 gene deletions and the GSTP1 SNP Ile105Val) in the association of HRV with the inflammatory risk factors second-hand smoke and obesity in the general population." (PMID 25133672, 2014).
Obesity (continued). "The GST Mu 1 (GSTM1) rs1056806 [C/T], GST theta 1 (GSTT1) rs17856199 [A/C], GST Pi 1 (GSTP1) rs1695 [A/G], and microsomal GST3 (mGST3) rs2065942 [C/T] variants of this family can impair the GSTs catalytic activities and are studied in multiple diseases, including obesity and related comorbidities." (PMID 33924357, 2021). "After stratification by gene deletion status, the OR for obesity was 5.75, (95%CI 2.25–14.7) among individuals with GSTT1 and GSTM1-deleted genotype, and 1.26, (95%CI 0.89–1.77) in carriers of both genes (p-interaction = 0.02)." (PMID 31999731, 2020). "This study is a first step towards the identification of biomarkers for early-stage obesity (GSTT1, GSTT3, GSTM1, MGST1, MGST3, SOD2, CAT) and glucose load (CRYM) in cattle." (PMID 30235219, 2018). "We found significant two-way interactions for the effect of high SHS exposure and GSTM1, GSTT1, GSTP1, and obesity on TP." (PMID 19057702, 2008). "Disparities in the frequency of GSTM1 and GSTT1 deletion and in the prevalence of obesity between populations worldwide, may partly explain differences in thyroid cancer incidence." (PMID 31999731, 2020).
cervical cancer (13 papers, 1994 to 2025). A primary or metastatic malignant neoplasm involving the cervix. "For example, the GSTM1 null genotype was associated with an increased risk of cervical cancer in Indian and Chinese populations." (PMID 39726707, 2024). "Stratified analysis showed that GSTM1 null (M1-) genotype was associated with a significantly better survival among patients with stage IIB cervical cancer (log-rank P = 0.004) than cases with stage IIIA/IIIB." (PMID 26571237, 2015). "All studies evaluating the association between GSTM1 polymorphisms and cervical cancer were included." (PMID 24391774, 2013). "Association of GSTT1 and GSTM1 deletions with esophageal and cervical cancer susceptibility is supported by data obtained by studying populations from India, Korea, Turkey, Great Britain, Italy, USA, and other countries." (PMID 23675381, 2013). "The GSTM1 “null” genotype also shows strong association with development of cervical cancer (OR = 6.50, p < 0.0001)." (PMID 23675381, 2013). "The overall result showed that the association between GSTM1 null genotype and risk for cervical cancer was statistically significant (OR = 1.56; 95%CI, 1.39–1.75)." (PMID 24391774, 2013). "Our results showed that smokers with null GSTM1 genotype had higher risk of cervical cancer (OR = 2.27, 95%CI, 1.46–3.54)." (PMID 24391774, 2013). "In view of the crucial role that the smoking play in the etiology of cervical cancer, the effect of the interaction of GSTM1 and GSTT1 polymorphisms and smoking on the development of cervical neoplasia has been conducted in several studies." (PMID 21629772, 2011). "GSTM1 null genotype has been found to incur an increased risk for primary cervical cancer in a mixed Caucasian, Hispanic and African-American patient population as compared to controls." (PMID 15790417, 2005). "Associations between GSTM1, T1 and P1 genetic polymorphisms and survival after treatment (CRT) for cervical cancer." (PMID 26571237, 2015). "Demographic and clinicopathological characteristics of cervical cancer patients (n = 227), and their distributions by genotypes of GSTM1, T1 and P1." (PMID 26571237, 2015). "The previous study reported that deletions of GSTT1 and GSTM1 genes play a significant role in development of esophageal or cervical cancers." (PMID 23675381, 2013). "During revision of the manuscript, a similar report investigating the association between GSTM1 and GSTT1 polymorphisms and cervical cancer risk was published." (PMID 21629772, 2011). "When the patients were stratified according to age, either GSTM1/T1 null genotype was significantly over represented in patients with cervical carcinoma who were = 40 years old." (PMID 15790417, 2005). "Research suggests that the null genotypes of GSTM1 and GSTT1 may elevate the risk of cervical cancer (CC) and ovarian cancer (OC) and are linked to factors associated with polycystic ovary syndrome (PCOS)." (PMID 40283113, 2025). "Our results do not show an association of GSTM1 or double mutants with cervical cancer or precursor lesions; GST-null mutants have been reported to be associated with oncologic diseases in general, though." (PMID 37891885, 2023). "A total of 227 cervical cancer patients with stages IIB-IIIB treated with the same chemoradiotherapy regimen were enrolled and genotyped for GSTM1, T1 and P1 gene polymorphisms by multiplex polymerase chain reaction (mPCR) and PCR-restriction fragment length polymorphism (PCR-RFLP)." (PMID 26571237, 2015).
oral cancer (13 papers, 2009 to 2024). "In conclusion, our meta-analysis indicates that CYP1A1 rs4646903, rs1048943, and null genotype of GSTM1 polymorphisms are possible risk factors for oral cancer, especially in Asians." (PMID 26166128, 2015). "For GSTM1 gene, null genotype appeared to be a risk factor for oral cancer (null vs present: OR 1.23, 95% CI 1.12–1.34), which was also proved in the subgroup analysis." (PMID 26166128, 2015). "With respect to GSTM1 polymorphisms, null genotype showed obvious relevance to oral cancer susceptibility (OR 1.23, 95% CI 1.12–1.34), especially in Asians (OR 1.27, 95% CI 1.15–1.41), compared with present genotype." (PMID 26166128, 2015). "Odds ratios (ORs) with 95% confidence intervals (CIs) were used to evaluate the relationship of CYP1A1 (rs4646903 and rs1048943) and GSTM1 polymorphisms with oral cancer risk." (PMID 26166128, 2015). "Another possibility is that both CYP1A1 and GSTM1 polymorphisms modify oral cancer risk in an ethnic-specific fashion due to different genetic backgrounds." (PMID 26166128, 2015). "Our meta-analysis was aimed to evaluate the association of CYP1A1 and glutathione-S-transferase M1 (GSTM1) polymorphisms with oral cancer susceptibility." (PMID 26166128, 2015). "In a population-based case-control study conducted in PR, the null GSTM1 genotype was associated with a marginally significant decrease in oral cancer risk (est." (PMID 19400958, 2009). "Therefore, it is significant to investigate the association of CYP1A1 and GSTM1 polymorphisms with oral cancer risk." (PMID 26166128, 2015). "The results demonstrated that CYP1A1 rs4646903 and null genotype of GSTM1 polymorphisms might serve as risk factors for oral cancer." (PMID 26166128, 2015). "A study conducted in 2015 suggested that the presence of GSTM1 and/or GSTT1 null genotypes, along with variant alleles of CYP1A1, might be the risk alleles for oral cancer in Pashtuns." (PMID 37710250, 2023). "Our previous meta-analyses concerning oral cancer suggest that GSTM1 null genotype increases the oral cancer risk in Asians but not Caucasians." (PMID 19338664, 2009). "However, the GSTM1 and GSTT1 null genotypes have been found to be associated with an increased risk of apical periodontitis and a significantly enhanced risk of developing oral cancer." (PMID 38419025, 2024). "Materials and Methods: Forty-eight subjects answered the Fagerström, and AUDIT tests and we studied them as likely screening tools for oral cancer and their correlation with the expression of CYP1A1, GSTM1, GSTP1, and GSTT1 genes by the RT-qPCR method." (PMID 35409669, 2022). "The analysis of the metabolism pathway of PAHs and oral cancer shows a significant gene–gene interaction effect (OR: 2.220 (95% CI: 1.166–4.225), p = 0.0201), and the main effect of each SNP is not significant (p = 0.2008 and 0.8915 for CYP1A1 and GSTM1, respectively)." (PMID 27045371, 2016).
ovarian carcinoma (12 papers, 2012 to 2025). A malignant neoplasm originating from the surface ovarian epithelium. "Considering these results, it might be predicted that polymorphisms of GST (GSTT1 or GSTM1) could provide a novel biomarker for early detection and diagnosis of ovarian cancer, although further research is necessary." (PMID 23319948, 2012). "Similarly, evaluation of GST functional polymorphisms (GSTT1, GSTM1) might help in detecting ovarian cancer at early stages, since they affect susceptibility and progression of cancer." (PMID 23319948, 2012). "No individual effect of GSTM1 or T1 genotypes was found but in combination, null genotypes of both were associated with poor survival in ovarian cancer." (PMID 26571237, 2015). "Also, considering the fact that carriers of low function GST genotypes (GSTT1 null, GSTM1 null) have a strong survival benefit, evaluation of GST polymorphisms could be promising biomarker for early detection of ovarian cancer." (PMID 23319948, 2012). "For the whole group of ovarian cancer patients the polymorphic variants in PGR, ABCB1, GSTT1, GSTM1 and GSTP1 genes did not change the risk of developing cancer." (PMID 25591549, 2015). "Moreover, the transcript levels of GSTM1 were found to be significantly correlated (* p < 0.05) with the PFS but not with the OS of the ovarian cancer patients." (PMID 35008958, 2022). "In ovarian cancer patients with a “double null” genotype, the observed prognosis was poor, along with diminished response to chemotherapy; however, patients with null genotypes for either GSTT1 or GSTM1 exhibited an increased survival rate after chemotherapy for invasive ovarian carcinoma." (PMID 23319948, 2012).
COVID-19 (11 papers, 2021 to 2025). A disease caused by infection with severe acute respiratory syndrome coronavirus 2. "Two candidate gene association studies reported the association of the GSTT1 and GSTM1 gene deletions with the COVID-19 outcomes." (PMID 36009328, 2022). "In addition, GSTM1 polymorphism regulates the susceptibility to many viral infections, including e.g. chronic hepatitis B, severe COVID-19, tick-borne encephalitis and human papillomavirus infections." (PMID 37993433, 2023). "A study investigating the relationship between GSTM1 and GSTT1 gene polymorphisms and COVID-19 severity and outcomes analyzed 269 RT-PCR-confirmed patients (149 mild, 120 severe cases)." (PMID 41209585, 2025). "Several studies have explored the association between GSTM1 and GSTT1 null genotypes and COVID-19 severity, but the evidence remains inconclusive." (PMID 40867811, 2025). "Beyond GSTM1 and GSTT1, other GST isoforms have also been investigated for their potential role in COVID-19 susceptibility and outcomes." (PMID 40867811, 2025). "Individuals with a lower frequency of GSTT1-null genotype showed higher COVID-19 mortality rates, while GSTM1-null genotype increased the odds of severe disease outcome." (PMID 37189435, 2023). "Taken together, the polymorphic studies reviewed in the current article revealed that GSTT1 and GSTM1-null genotypes show differential behavior against COVID-19 mortality." (PMID 37189435, 2023). "Another study showed that the frequency of GSTM1−/−, GSTT1−/−, and GSTM1−/−/GSTT1−/− was higher in severe COVID-19." (PMID 37111348, 2023). "The results indicated that the frequencies of GSTM1−/−, GSTT1−/− and GSTM1−/−/GSTT1−/− were more pronounced in patients with severe COVID-19 symptoms than those with mild." (PMID 37189435, 2023). "So far, it has been revealed that GSTT1- and GSTM1-null genotypes have differential behavior versus COVID-19 mortality." (PMID 34988113, 2021). "GSTM1 and GSTT1 gene deletions as well as GSTP1 rs1138272 and rs1695, GSTA1 rs3957357, and GSTM3 rs1332018 polymorphisms have been investigated in a cohort of 207 COVID-19 patients and 252 healthy individuals of Serbian, Caucasian origin." (PMID 36009328, 2022). "Instead, we found that GSTM3, known to be in linkage disequilibrium with GSTM1, meaning it might influence GSTM1 expression and possess overlapping substrate specificity with GSTM1, significantly contributes to COVID-19 development." (PMID 34988113, 2021). "As GSTM1 and GSTT1 deletions have been associated with alterations in enzyme activity and risk of pulmonary fibrosis, a severe symptom of COVID-19, it was suggested that they might be used as predictors of COVID-19 morbidity and mortality." (PMID 36009328, 2022). "Since the frequency of GSTM1−/−, GSTT1−/−, and GSTM1−/−/GSTT1−/− is higher in severe COVID-19 patients and the aggressive forms of periodontitis were associated with the double null GSTM1 and GSTT1 combination." (PMID 36366382, 2022). "The distribution of polymorphisms in cytosolic glutathione S-transferases GSTA1, GSTM1, GSTM3, GSTP1 (rs1695 and rs1138272), and GSTT1 were assessed in 207 COVID-19 patients and 252 matched healthy individuals, emphasizing their individual and cumulative effect in disease development and severity." (PMID 34988113, 2021). "Results showed that the ACE-DD genotype of ACE2, (GSTM1+/+) (GSTT1−/−) genotype of GST gene, and CA genotype (heterozygosity) of miR-423 rs6505162 genes, which were found in the patient, could be independent risk factors of severe COVID-19, even without comorbidities." (PMID 35371838, 2022).